PRAMEF10 (PRAME family member 10)
Tractability: PROTAC: ubiquitination databases record sites on it.
Gene: Protein-coding gene on chromosome 1 (12,892,250 to 12,898,270, reverse strand). Ensembl gene ENSG00000187545.
Gene Ontology:
Molecular function: protein binding; ubiquitin-like ligase-substrate adaptor activity
Biological process: proteasome-mediated ubiquitin-dependent protein catabolic process; negative regulation of apoptotic process; negative regulation of cell differentiation; negative regulation of DNA-templated transcription; positive regulation of cell population proliferation
Cellular component: Cul2-RING ubiquitin ligase complex; cytoplasm
Genetic constraint (gnomAD): Loss-of-function variants: 4 observed, 12.23 expected, observed/expected ratio (o/e) 0.33, 90% interval 0.16 to 0.75. The synonymous counts are far from expectation, so gnomAD's model fits this gene poorly and the ratio says little. Missense variants: 93 observed, 197.21 expected, observed/expected ratio (o/e) 0.47, 90% interval 0.4 to 0.56. Synonymous variants: 43 observed, 75.99 expected, observed/expected ratio (o/e) 0.57, 90% interval 0.44 to 0.73.
Homologues: Orthologues: mouse Pramel12 (45% identical), rat Pramef8 (44% identical), rat Pramef5 (41% identical), mouse Pramel20 (40% identical), mouse Pramel13 (40% identical), mouse Pramel43 (40% identical), mouse Gm13040 (39% identical), mouse Gm13043 (39% identical), mouse Gm13057 (39% identical), mouse Pramel16 (39% identical), mouse Pramel31 (39% identical), rat LOC120103107 (39% identical), and 78 more. Paralogues in human: PRAMEF33 (99% identical), PRAMEF17 (88% identical), PRAMEF18 (62% identical), PRAMEF19 (62% identical), PRAMEF1 (60% identical), PRAMEF14 (59% identical), PRAMEF13 (59% identical), PRAMEF2 (58% identical), PRAMEF12 (53% identical), PRAMEF8 (53% identical), PRAMEF7 (53% identical), PRAMEF20 (50% identical), and 12 more.